ELL (elongation factor for RNA polymerase II)
Description:
Elongation factor component of the super elongation complex (SEC), a complex required to increase the catalytic rate of RNA polymerase II transcription by suppressing transient pausing by the polymerase at multiple sites along the DNA. Elongation factor component of the little elongation complex (LEC), a complex required to regulate small nuclear RNA (snRNA) gene transcription by RNA polymerase II and III. Specifically required for stimulating the elongation step of RNA polymerase II- and III-dependent snRNA gene transcription. ELL also plays an early role before its assembly into in the SEC complex by stabilizing RNA polymerase II recruitment/initiation and entry into the pause site. Required to stabilize the pre-initiation complex and early elongation.
Synonyms: C19orf17; Men; ELL1; PPP1R68
Tractability: PROTAC: ubiquitination databases record sites on it; its protein half-life has been measured.
Gene: Protein-coding gene on chromosome 19 (18,442,663 to 18,522,116, reverse strand). Ensembl gene ENSG00000105656.
Subcellular location: Nucleus; Nucleus speckle; Nucleus, Cajal body
Subcellular location (Human Protein Atlas): Nucleoplasm; Cytosol; Nuclear bodies
Pathways (Reactome):
Disease: Formation of HIV elongation complex in the absence of HIV Tat; Formation of HIV-1 elongation complex containing HIV-1 Tat; HIV elongation arrest and recovery; Pausing and recovery of HIV elongation; Pausing and recovery of Tat-mediated HIV elongation; Tat-mediated HIV elongation arrest and recovery; Tat-mediated elongation of the HIV-1 transcript
Gene expression (Transcription): Formation of RNA Pol II elongation complex; RNA Polymerase II Pre-transcription Events; RNA Polymerase II Transcription Elongation; RNA polymerase II transcribes snRNA genes
DNA Repair: Transcription-Coupled Nucleotide Excision Repair (TC-NER)
Gene Ontology:
Molecular function: phosphatase binding; protein binding; cis-regulatory region sequence-specific DNA binding
Biological process: positive regulation of transcription by RNA polymerase III; positive regulation of transcription elongation by RNA polymerase II; snRNA transcription by RNA polymerase II; snRNA transcription by RNA polymerase III; positive regulation of DNA-templated transcription, elongation; positive regulation of snRNA transcription by RNA polymerase II; transcription elongation by RNA polymerase II
Cellular component: Cajal body; euchromatin; histone locus body; nuclear body; nuclear speck; nucleoplasm; nucleus; transcription elongation factor complex
Genetic constraint (gnomAD): Loss-of-function variants: 19 observed, 59.83 expected, observed/expected ratio (o/e) 0.32, 90% interval 0.22 to 0.47. The upper end of that interval is the gene's LOEUF score, 0.47, which puts it in group 2 of 6, group 1 being the genes least tolerant of losing a copy. Missense variants: 795 observed, 807.82 expected, observed/expected ratio (o/e) 0.98, 90% interval 0.93 to 1.04. Synonymous variants: 399 observed, 352.33 expected, observed/expected ratio (o/e) 1.13, 90% interval 1.04 to 1.23.
Cancer hallmarks: cell replicative immortality (promotes); angiogenesis (suppresses); suppression of growth (promotes)
Homologues: Orthologues: chimpanzee ELL (99% identical), macaque ELL (97% identical), dog ELL (88% identical), pig ELL (87% identical), rat Ell (82% identical), mouse Ell (81% identical), guinea pig ELL (75% identical), tropical clawed frog ell (66% identical), zebrafish ell (59% identical), Drosophila melanogaster Su(Tpl) (25% identical), Caenorhabditis elegans ell-1 (15% identical). Paralogues in human: ELL2 (48% identical), ELL3 (20% identical), MARVELD2 (17% identical), OCLN (14% identical), OCEL1 (8% identical).
Diseases named in the same sentence as ELL in open-access papers:
ELL is named in the same sentence as 39 diseases in open-access papers, as found by Europe PMC text mining. Sharing a sentence is not in itself a finding about the gene and the disease. The quoted sentences say what the papers report.
leukemia (18 papers, 2014 to 2025). A malignant (clonal) hematologic disorder, involving hematopoietic stem cells and characterized by the presence of primitive or atypical myeloid or lymphoid cells in the bone marrow and the blood. "ELL-associated factors 1 and 2 (EAF1/2), a class of tumor suppressor genes interacting strongly with eleven-nineteen lysine-rich leukemia (ELL), can inhibit a variety of cancers in organisms, including leukemia and prostate cancer." (PMID 37002435, 2023). "Although there are > 70 documented fusion partners of MLL1, transcription cofactors AF4 (also known as AFF1) and its paralog AFF4, AF9 and its paralog ENL, and ELL are found in > 70% MLL1-r leukemias." (PMID 33823889, 2021). "The SNP NC_031986.2:34590018 is found in an intronic region of the Elongation Factor ELL (Eleven-Nineteen Lysine-Rich Leukemia), which has been described as a selective co-regulator for steroid receptor functions." (PMID 31416805, 2019). "Several MLL translocations and components of the SEC complex, including P-TEFb, AF9 and ELL, have been described in various leukemias, suggesting that transcription is misregulated in leukemias." (PMID 24576043, 2014). "AFF4 directly binds to the P‐TEFb subunit cyclin T1, and to the other SEC subunits including one of the ELL proteins ELL or ELL2, to eleven‐nineteen leukemia (ENL) or ALL1‐fused gene from chromosome 9 (AF9), and to one of the ELL‐associated factor proteins EAF1 or EAF2." (PMID 39582094, 2024). "The spatial positioning of MLL (mixed-lineage-leukemia or myeloid-lymophoid-leukemia, now renamed as KMT2A) and MLL-related genes, including AF4, AF6, AF9, ENL, and ELL (the most common translocating partner of MLL), can be the possible contributing factors of human leukemias." (PMID 37426200, 2023). "Most frequent MLL1-fusion partners AF4/AFF4, AF9/ENL and ELL, together with CDK9/cyclin-T1, constitute super elongation complexes (SEC), which promote aberrant gene transcription, oncogenesis and maintenance of MLL1-rearranged (MLL1-r) leukemia." (PMID 35395864, 2022). "Despite > 70 fusion partners of MLL1 were identified, only a few are frequently found in ~ 70% MLL1-r leukemias, including transcription cofactors AF9 (also known as MLLT3) and its paralog ENL (also known as MLLT1), AF4 and its paralog AFF4, and ELL." (PMID 35395864, 2022). "Further investigation using MLL1-AF4 and AFF4 with deletion of various AF4/AFF4 domains showed that only the CHD domain of AFF4/AF4 is required for leukemic transformation, while other AF4/AFF4′s interacting domains with P-TEFb, ELL and AF9/ENL are dispensable for MLL1-AF4/AFF4 leukemia." (PMID 33823889, 2021).
psoriasis (3 papers, 2023 to 2025). An autoimmune condition characterized by red, well-delineated plaques with silvery scales that are usually on the extensor surfaces and scalp. "The elongation factor gene (ELL) showed upregulation in blood with psoriasis-associated alleles, and is thought to sustain the epidermal proliferation genes known to be upregulated in psoriasis." (PMID 38785955, 2024). "We also identified five novel psoriasis risk genes, methionine sulfoxide reductase A, elongation factor for RNA polymerase II (ELL), Myotubularin Related Protein 9 (MTMR9), leucine-rich repeat containing 25 (LRRC25), and single-stranded-DNA-binding protein 4 (SSBP4), among 26 genes." (PMID 37511476, 2023). "The elongation factor gene ELL, which maps to the newly identified 19p13.11 locus, is predicted by TWAS to be upregulated in blood in the presence of psoriasis-associated alleles." (PMID 40021644, 2025). "In this study, we identified three novel genes associated with psoriasis after the conditional and joint analysis: LRRC25, SSBP4, and ELL." (PMID 37511476, 2023).
breast carcinoma (2 papers, 2024 to 2025). "These targets (FGFR2, PTLH, ELL, and ZMIZ1) have already been identified through meta-GWAS of breast cancer." (PMID 40938940, 2025).
colon cancer (2 papers, 2016 to 2021). "ELL has been identified as a potential tumor suppressor by interacting with c-Myc and suppresses colon tumor xenograft growth." (PMID 34035992, 2021). "Given that overexpression of ELL inhibited xenograft tumour growth and ELL expression was negatively correlated with c-Myc expression in human colon cancer specimens, the suppressive role of ELL on tumour growth might also be mediated by c-Myc." (PMID 27009366, 2016). "Furthermore, overexpression of ELL in HCT116 colon cancer cells inhibited cell proliferation and xenograft tumour growth in nude mice." (PMID 27009366, 2016). "In addition, ELL expression was decreased in human colon cancer specimens compared with normal tissues, and was negatively correlated with c-Myc expression." (PMID 27009366, 2016). "In contrast, the frequency of ELL-positive staining decreased in colon cancer specimens compared with the non-tumour containing tissues (37.7% versus 65.12%, respectively)." (PMID 27009366, 2016).
chronic myelomonocytic leukemia (1 paper, 2015). A myelodysplastic/myeloproliferative neoplasm which is characterized by persistent monocytosis, absence of a Philadelphia chromosome and BCR/ABL fusion gene, fewer than 20 percent blasts in the bone marrow and blood, myelodysplasia, and absence of PDGFRA or PDGFRB rearrangement. "Type 2 was so far found in only a single case of chronic myelomonocytic leukemia (CMML) that transformed to AML; it had exon 3 of ELL fused to 5 ́-MLL." (PMID 26949571, 2015).
lentivirus infection (1 paper, 2016). Virus diseases caused by the Lentivirus genus. "To further demonstrate the biological function of ELL in mediating c-Myc degradation and inhibiting its transcriptional activity, we examined its effect on cell proliferation using three stable HCT116 cell lines generated by lentivirus infection, control, ELL and ELL(C595A)." (PMID 27009366, 2016).
Obesity (1 paper, 2018). Accumulation of substantial excess body fat. "Instead, our screen suggests that different nearby cis gene may be more fruitful for further functional follow up for obesity, namely ZCCHC8, VPS33A, RSRC2; SPDEF, NUDT3; SETD1, VKORC1; SGSM2, SRR; VASP, SIX5; OTX1; BANK1; ARIH1; ELL; CHST8, respectively." (PMID 29608557, 2018).
periodontitis (1 paper, 2023). An acute or chronic inflammatory process that affects the tissues that surround and support the teeth. "In addition, we discovered TFs, E2F3, ELL and ARID3A are up-regulated in periodontitis tissues compared with the healthy control, however, there was no statistical significance, there may be shortcomings of small sample size." (PMID 37495990, 2023).
tauopathy (1 paper, 2024). Neurodegenerative disorders involving deposition of abnormal tau protein isoforms (tau proteins) in neurons and glial cells in the brain. "Lastly, it may also be affecting EOAD through a functional relationship with ELL, which is enriched in LOAD and tauopathy in STRING human phenotypes." (PMID 38883718, 2024).
Type 2 diabetes (1 paper, 2020). "Thus, we describe a pathway of regulating stability and functions of key elongation factor ELL for expression of diverse sets of genes, including ones that are linked to Type 2 diabetes pathogenesis." (PMID 32152128, 2020). "Further studies, using a large cohort of patients as well as animal models, would be required for in-depth understanding of the overall effect of reduced DBC1 and ELL expression and its implications in Type 2 diabetes pathogenesis." (PMID 32152128, 2020). "Consistently, Type 2 diabetes patient-derived peripheral blood mononuclear cells show reduced expression of DBC1 and ELL and associated key target genes required for glucose homeostasis." (PMID 32152128, 2020). "Notably, deregulation of a substantial number of genes that are coregulated by DBC1 and ELL has been predicted to be involved in giving rise to several diseases, including Type 2 diabetes." (PMID 32152128, 2020).
cancer (9 papers, 2006 to 2025). A tumor composed of atypical neoplastic, often pleomorphic cells that invade other tissues. "ELL also plays a role in hypoxia response in cancer cells, where HIF-1alpha and ELL seem to modulate each other’s function." (PMID 36293446, 2022). "Overall, these analyses recapitulate many of the already described markers of EMT transformation, and also suggest that ELL and NCKIPSD mutations may affect the cancer cell’s ability to undergo EMT transformation." (PMID 36774358, 2023). "ELL(C595A) also lost its ability to inhibit cancer cell proliferation and xenograft tumour growth." (PMID 27009366, 2016). "We found telomere maintaining genes (TERF2, CTC1, and ACD), genes involved in zinc homeostasis (MTF1 and SLC30A9), transcription elongation factor complex components (ICE1, ICE2, ELL), and BCL6 corepressors (BCOR, BCORL1) uniquely invoked in TNBC cancers." (PMID 40700427, 2025).
tumor (6 papers, 2009 to 2023). "Thus, ELL(C595A) mutant might promote tumour metastasis through inducing these metastasis-associated genes." (PMID 27009366, 2016). "We found six heterozygous variants predicted to alter splicing; two in DNA repair-associated genes (BRCA1 and BAP1) and four in tumor suppressor genes (ARHGEF10L, ELL, MYH9, and NCOR2)." (PMID 37234870, 2023). "ELL-mediated c-Myc degradation inhibits c-Myc-dependent transcriptional activity and cell proliferation, and also suppresses c-Myc-dependent xenograft tumour growth." (PMID 27009366, 2016). "In contrast, the ELL(C595A) mutant not only loses the ability to inhibit cell proliferation and xenograft tumour growth, but also promotes tumour metastasis." (PMID 27009366, 2016). "To figure out the mechanisms regarding why the ELL(C595A) mutant promotes tumour metastasis, initially, we performed cell invasion assays." (PMID 27009366, 2016). "A recent work reported that eleven–nineteen lysine-rich leukemia (ELL) could also function as an E3 ubiquitin ligase, target Myc proteasomal degradation and suppress tumor growth." (PMID 36003390, 2022). "Thus, our work reveals a previously unrecognized function for ELL as an E3 ubiquitin ligase for c-Myc and a potential tumour suppressor." (PMID 27009366, 2016). "It seems that the protein level of c-Myc protein varied among ELL(C595A) mutant xenograft tumours." (PMID 27009366, 2016). "Therefore, it appears that the E3 ubiquitin ligase activity of ELL is particularly required for its tumour suppressive function." (PMID 27009366, 2016). "Therefore, ELL(C595A) mutant might promote tumour metastasis through inducing expression of metastasis-associated genes, particularly for inducing S100A4, a well-defined metastasis-promoting gene." (PMID 27009366, 2016). "Clearly, we still cannot rule out that additional ELL substrates, except for c-Myc, play roles in mediating ELL's function in tumour suppression." (PMID 27009366, 2016). "Due to no obvious tumours were formed in mice with injections of ELL-overexpressing HCT116 cells, we excluded this cell line but added HCT116 parental cells as another control." (PMID 27009366, 2016). "Interestingly, expression of most of the fusion partners including the high‐frequency partners like AFF1, MLLT1, MLLT3, MLLT10, ELL, and MLLT4, were positively correlated with MLL1 expression irrespective of the tumor type." (PMID 30548174, 2019).
infection (3 papers, 2016 to 2019). The state of being infected such as from the introduction of a foreign agent such as serum, vaccine, antigenic substance or organism. "ELI genes were typically highly expressed in the mycelia stage while a large number of ELL genes were up-regulated in the infection stage." (PMID 31017897, 2019). "In contrast, 31% of the ELL genes were up-regulated while 15% were down-regulated during infection." (PMID 31017897, 2019). "Unfortunately, when these cell lines went through the third-round infection with the lentiviruses expressing ELL or ELL(C595A) mutant as well as ELL-shRNA, the cells became very unhealthy (the most of cells were broken) for unknown reasons." (PMID 27009366, 2016). "Overexpression of ELL via lentivirus infection suppressed Rat1 cell proliferation significantly." (PMID 27009366, 2016).
ELL also shares sentences with these, for which no sentence is quoted: acute myelogenous leukemia (5 papers); myeloid sarcoma (2); prostate carcinoma (2); acute leukemia (1); acute lymphoblastic leukemia (1); acute monoblastic leukemia (1); acute promyelocytic leukemia (1); Burkitt lymphoma (1); Cachexia (1); central nervous system leukemia (1); chondroblastoma (1); dementia (1); giant cell tumor of bone (1); granulocytosis (1); kidney disease (1); lung carcinoma (1); megakaryoblastic leukemia (1); melanoma (1); multiple endocrine neoplasia type 1 (1); myelodysplastic syndrome (1); ovarian carcinoma (1); Parkinson’s (1); renal cell cancer (1); renal tumours (1); Stroke (1); thyroid nodule (1).